CCL21 (C-C motif chemokine ligand 21)
Diseases named in the same sentence as CCL21 in open-access papers (continued):
Sharing a sentence is not in itself a finding about the gene and the disease.
tumor (continued). "RNA expression of CCL21 was analyzed in 18 primary therapy-naïve tumor samples, and the expression levels were correlated with the immunohistochemical staining of the CD4+- and CD8+-infiltrating T cells in eight tissue samples for which sufficient FFPE material was still available." (PMID 27369431, 2016). "Moreover, ascophyllan treatment induced up-regulation of CCR7 in DCs and its ligands CCL19 and CCL21 in spleen in tumor-bearing mice." (PMID 27008707, 2016). "This correlation suggests that testing for CCL21 levels in therapy-naïve EWS tumor samples could be used as a prognostic marker and supports a potential role for this cytokine in anti-tumor immunity." (PMID 27369431, 2016). "This tumor entity could therefore serve as a good target for an immunotherapy approach based on the use of CCL21." (PMID 27369431, 2016). "LN lymphangiogenesis and cellular contents may be easily influenced by growth factors, cytokines, and chemokines, e.g., vascular endothelial growth factor (VEGF)-A and CCL21 secreted by cancer cells and stromal cells in tumor microenvironment." (PMID 28036019, 2016). "In patients with CCL21-expressing cells present in or around the tumor, chemotherapy could enhance the anti-tumor immunity and subsequently lead to a better chemotherapeutic response." (PMID 27369431, 2016). "Studies in mouse models suggest that CCL21 secreting tumors may alter the locally generated immune response by promoting tumor-induced tolerance, which facilitates tumor progression." (PMID 25884667, 2015). "Interestingly, direct intratumoural injection of CCL21 secreting dendritic cells recruited and primed naive tumor reactive T cells within the tumor and resulted in reduced tumor growth." (PMID 26155419, 2015). "The administration of IL-12 and GM-CSF-expressing adenovirus (Ad-ΔB7/IL12/GMCSF) in combination with DCs in B16-F10 melanoma tumor-bearing mice also showed increased DC migration to draining lymph nodes due to the upregulation of CCL21+ lymphatic vessels around tumor tissues." (PMID 26690204, 2015). "Taken together, majority of discoveries support a role of CCL21 in anti-tumor immunity, however concerns remain that tumor-derived CCL21 may induce immune tolerance to tumor antigens in some models." (PMID 24810425, 2014). "Indeed, a significant increase in migratory response toward CCL21 was observed in LMW HA primed tumor-pulsed monocyte-derived dendritic cells (DC/TL/LMW HA) when compared to LWM HA untreated cells (DC/TL)." (PMID 25238610, 2014). "This suggests that the recruitment of DCs in patient tumor tissue could be achieved by local expression of CCL21." (PMID 24810425, 2014). "PCR-based approaches, such as combining analyses of a combination of mature FDC markers, HEV markers and TLS associated chemokines such as CCL19, CCL21 and CXCL13, could also decrease the chance of missing TLS-positive tumours." (PMID 25177210, 2014). "On the other hand, tumor-infiltrated T cells can express CCL21." (PMID 25505783, 2014). "In the present study we demonstrated that LMW HA represents a potent stimulator of migration toward lymph node for human DC obtained from both HD and CRC patients, likely partially involving CCR7/CCL21 axis and inducing resistance to IL-8, a tumor-derived DC chemoattractant." (PMID 25238610, 2014). "Studies by other investigators confirmed the anti-tumor activity of CCL21 in several tumor models." (PMID 24810425, 2014). "The induction of immune response may be tumor/environment-specific or dependent on timing and amount of CCL21 released." (PMID 24810425, 2014). "The different growth course of tumor in above two experiments may be explained by the different cancer cells used and the different CCL21 amount released in the study." (PMID 24810425, 2014).
tumor (continued). "Following encounter with foreign or tumor antigen, DCs become activated (mature), capture antigen, migrate to lymphoid tissues in response to chemokines such as CCL21, and undergo physiological change to present antigen in association with major histocompatibility complex (MHC) to T cells." (PMID 24810425, 2014). "DC-CCL21 treatment led to reduced tumor burden compared to control DC and recombinant CCL21 groups." (PMID 24810425, 2014). "Interestingly, at least with 4 vaccine studies (VEGFR2, VEGF-A, bFGF, survivin/CCL21) tumor angiogenesis was markedly inhibited, but these vaccines did not interfere with normal physiologic processes in several studies." (PMID 21385454, 2011). "These defects, which did not require tumor invasion, correlated with loss of fibroblastic reticular cells in T cell zones and in impaired production of CCL21." (PMID 21811640, 2011). "CCL21 can attract immune cells and inhibit vascularization, which block tumor growth." (PMID 21548969, 2011). "In tumor-challenged wildtype littermates, large areas of CCL21 positive cells were detected throughout the lymph node cortices, and pan-keratin positive patches of metastatic tumor cells in the lymph nodes were co-localized with CCL21 immunoreactivity (middle row)." (PMID 21172016, 2010). "More generally CCL21 may work in synergistic and redundant manners with other chemokines produced by lymphatic endothelium to facilitate lymphatic invasion by tumor cells that over-express chemokine cognate receptors." (PMID 21172016, 2010). "Hence, it is likely that the mechanism of CCL21 mediating migration of tumor cells to lymph nodes from primary site arising from its attraction to CCR7, which is highly expressed by primary tumors, is similar to the mechanism of the lymphocytes' homing effect." (PMID 20181250, 2010). "Some CCL21 staining showed spotty co-localization with LYVE-1 along the walls of lymphatic vessels in the lymph nodes, although most immunolocalization of the chemokine ligand was associated with metastatic tumor cells." (PMID 21172016, 2010). "Since CCL21 is produced by lymphatic endothelium, and known to drive lymphatic-directed immune cell traffic, it has been hypothesized that tumor cells may usurp this pathway in order to drive lymphatic invasion by over-expressing the CCR7 receptor." (PMID 21172016, 2010). "In addition, intratumoral injections of CCL21-transduced DC into established murine lung tumors resulted in complete regression and protective anti-tumor immunity." (PMID 18644162, 2008). "Given that IP-10/CXCL10 and MIG/CXCL9 are important for CCL21-DC mediated tumor regression in murine studies, we examined whether AdCCL21 transduction increased the expression of these chemoattractants in human DC." (PMID 18644162, 2008). "Therefore, we anticipate that intratumoral delivery of CCL21-DC will induce effective chemotaxis in vivo, increase anti-tumor immune effector cells, and limit T regulatory cell trafficking." (PMID 18644162, 2008). "We previously reported the potent anti-tumor properties of CCL21 in murine cancer models." (PMID 18644162, 2008). "CCL21-DC will have access to the entire repertoire of tumor antigens in situ." (PMID 18644162, 2008). "In addition, the CCL21-DC will exploit the professional APC as a vehicle for cytokine delivery, capitalizing on the capacity of CCL21 to attract both endogenous host DC and T lymphocytes to the tumor site to restore local immune reactivity." (PMID 18644162, 2008). "Furthermore, CCL21 was implicated in increasing expression of naïve T cells and dendritic cells in the TME and B cell activation, resulting in organization of TLSs and potentiation of anti-tumor immunity." (PMID 40940789, 2025). "In line with our findings related to the disruption of the CCR7-CCL19/CCL21 axis and a significant reduction in the LECs, irradiated lymph nodes in our model were severely depleted of cross-presenting cDC1, a subset of DCs orchestrating the development of anti-tumor immunity." (PMID 38951172, 2024).
tumor (continued). "In addition to promoting CD93 expression in pMCs, the tumor also activates the CD93 pathway in pMCs because we found that C1q was responsible for CD93-mediated inhibition of CCL21 production by pMCs, and the C1q level was enhanced in both mice with lung tumors and lung tumor patients." (PMID 38250037, 2024). "However, in DC-based immunotherapy, injection of CCL21 can promote tumor regression." (PMID 37215990, 2023). "Since CCL21 was detectable in MC38 tumors by immunohistochemical analysis, it is possible that the tumor growth of MC38 in CCL21a-KO mice is due to decreased infiltration of M1 macrophages by CCL21-Ser deficiency, resulting in a reduced anti-tumor immune response." (PMID 37664721, 2023). "Meanwhile, CCL21/CCL19 attract CCR7 + T cells as well as other immune cells and alter the ectopic lymph node structure associated with cancer prognosis by co-localizing synaptic cells and T cells, thereby promoting immune activity in the tumor microenvironment (TME) leading to immune infiltration." (PMID 37864213, 2023). "Additionally, the stimulation by CCL19 or CCL21 led to overexpression of CCR7 on the tumor cells and promoted cancer cell migration and infiltration into lymph nodes, which have been confirmed by the observation that increased CCR7 on cancer cell enhanced metastasis from breast to lung." (PMID 35359417, 2022). "Thus, VEGF-C may render a more lymphatic invasive tumor cell phenotype via activation of the CCL21/CCR7 signaling axis." (PMID 35203305, 2022). "Furthermore, VEGF-C increased tumor cell invasion to lymphatic endothelial cells that could be prevented by blocking either CCL21 or CCR7." (PMID 35203305, 2022). "Because the injection of CXCL13 and CCL21 indicated a potential antitumor immune activity in orthotopic tumors, we explored whether coadministration of chemotherapy to induce tumor cell death, and perhaps release of tumor antigens, could impact tumor dynamics." (PMID 34252585, 2021). "The combination treatment caused increased secretion of CCL2, CCL21, CXCL1, CXCL2, CXCL5, CXCL9 and CXCL16, whereas the levels of CCL11, CCL17, CCL19, CCL22, CCL25, CCL27 and CX3CL1, which are associated with protumourigenic effects, were decreased in the tumours." (PMID 33014356, 2020). "In addition, CCL21 stimulates these immune cells to produce cytokines such as interferon-γ, granulocyte-macrophage colony-stimulating factor, and interleukin-12, facilitating T cell activation and subsequently inhibiting tumor growth." (PMID 29687228, 2020). "We also found that CXCL12, CCL27, and CCL21 were found in higher quantities in the healthy adjacent tissue (1795.6 ± 700 pg/ml, 242.9 ± 95 pg/ml, and 17285.9 ± 6000 pg/ml, respectively) than in the tumor (325.8 ± 72 pg/ml, 56.7 ± 20 pg/ml, and 2313.6 ± 1,000 pg/ml, respectively)." (PMID 31105699, 2019). "Interestingly, CCL21 expression is decreased in invaded lymph node compared to non-invaded lymph node that may suggest an escape mechanism to avoid tumor immune infiltration, specifically by CCR7 expressing T cells and DC." (PMID 30420855, 2018). "This invites the attractive speculation that CCL21+ lymphatic vessels in and around tumor TLSs could provide major trafficking systems guiding activated immune cells to local tumor-draining LNs where systemic protection against metastatic dissemination of primary tumor cells could be established." (PMID 29312327, 2017). "Numerous evidences have shown that CCL21 could boost anti-tumor immunity." (PMID 27783999, 2017). "Likewise, expression of CCL21 in the tumor promotes immune escape and tumor progression, which may be explained, at least in part, by the enhancement of naïve T cell recruitment." (PMID 28127298, 2016). "Similarly, the over-expressed chemokines CCL19 and CCL21 may be expressed by the tumor cells, whereas their CCR7 receptor may be expressed by licensed DC or (less typically) by naive and central memory T cells." (PMID 27386846, 2016).
tumor (continued). "In addition, CCL21 may increase dendritic cell-provoked T cell responses, leading to more efficient anti-tumor immune responses." (PMID 27369431, 2016). "However, the expression of both CCR7 and CCL21 in gastric cancer may indicate a poorer prognosis through lymph node metastasis illustrating how context/tumor type-dependent chemokine expression may be with regard to prognosis." (PMID 24762633, 2014). "However, the results of interaction between DCs and tumor cells could be multifaceted based on CCR7/CCL19 or CCR7/CCL21 interaction." (PMID 25110692, 2014). "Thus, the ability of CCL21 to promote T cell activation through the cognate interaction of recruited T lymphocytes and DC has potential to circumvent tumor-mediated immune suppression and orchestrate effective T cell-mediated anti-tumor activity." (PMID 24810425, 2014). "In addition, we show that lymphatic cell-surface HS may serve as a source for the establishment of CCL21 gradients that drive tumor cell migration." (PMID 21172016, 2010). "(c) Signaling molecules also play a role, as the density of tumor-infiltrating T cells is negatively associated with expression of VEGF, B7-H1/PD-L1 and endothelin B receptor by tumors and positively associated with expression of the chemokines CXCL9, CCL21, CCL22, CCL2 and CCL5." (PMID 19641607, 2009). "Our in vitro experiments revealed that exogenous CCL21 administration elevated p-ERK1/2 expression, promoting tumor proliferation and invasion." (PMID 39735670, 2025). "The increase in T cells in the TME after aCD40 treatment was possibly due to the increase in the production of chemokines such as CCL5, CCL21, CXCL9, and CXCL10 within the tumor." (PMID 40585246, 2025). "Compared with the peritumor area, CCL21, CCL19 and Pecam1 were more highly expressed in the tumor area, whereas Lyve1 had lower expression." (PMID 40685403, 2025). "Taken together this suggests CCL21 and VEGFC protein content in tumor-draining PALNs shifts in a predictable manner with mRNA expression of the tumor and with the extent of ablation of the tumor after SA-HFIRE." (PMID 39998766, 2025). "Abundance of LA in the tumor exterior vs tumor interior in our and other studies can drive the migration of immature DCs along outward CCL19/CCL21 gradients, and their accumulation and maturation within LA in peritumoral compartments (OM, PT)." (PMID 41410751, 2025). "A recent study using mouse models has revealed that VEGFC activates the CCL21/CCR7 signaling pathway, which promotes the activation and recruitment of naïve T cells to the tumor." (PMID 38980684, 2025). "Similar findings have been reported with dual armoring with IL-7 and CCL21, another CCR7 ligand, which also promoted T-cell and DC recruitment, increased central memory phenotype T-cells, and improved tumor control in an antigen-heterogeneous tumor model." (PMID 41019052, 2025). "CCL21 and VEGFC were measured using ELISA to assess the protein content of downstream PALNs at day 1 and 3, based on previous vascular remodeling in the tumor and TDLNs." (PMID 39998766, 2025). "In mice with established subcutaneous B16.F0 tumors, peritumoral injection of CXCL13 and CCL21, combined with intraperitoneal anti–PD-L1 therapy, increased intratumoral TLS formation and significantly enhanced tumor suppression." (PMID 40940789, 2025). "In line with the phenotype data, tumor-primed cDC2s exhibited a lower migratory capacity toward the chemokines CCL19 and CCL21 compared with untreated mature cDC2s." (PMID 40986321, 2025). "They demonstrated that CAR T-cells armored with LIGHT upregulated expression of chemokines CCL19, CCL21, and CXCL13 in both stromal cells and tumor cells, enhancing the ability of the stromal cells to recruit T-cells in migration assays." (PMID 41019052, 2025). "We analyzed the transcriptome data of tumor tissues from 10 HCC patients with different responses and the results showed that CCL21 expression was upregulated in patients with response to immunotherapy." (PMID 38367070, 2024).
tumor (continued). "In the well-characterized TRAMP mouse model of PCa, the direct expression of CCL21 in the prostate TME increased CD8 T cells and DC, thereby inhibiting tumor growth and metastasis." (PMID 39766038, 2024). "CCL21 further impairs NKT survival and function, inhibiting NKT migration in vitro toward tumor-conditioned hypoxic monocytes and preventing their localization to neuroblastoma grafts in mice." (PMID 39588373, 2024). "Here, we analyzed the transcriptome data of tumor tissues from 10 HCC patients with different response to immunotherapy and found that there was significant upregulation of CCL21 expression in the HCC tissues of patients that responded to immunotherapy." (PMID 38367070, 2024). "CCL21 recruited T-cells and dendritic cells, while CDD-iRGD triggered tumor cell apoptosis, activating the host’s immune response." (PMID 39351063, 2024). "Bulk RNA sequencing and histological assessment of high-tumor-burden follicular lymphoma tissues demonstrate a significant correlation between LTB, TGFB1, and CCL21 expression." (PMID 38038708, 2024). "High levels of CCL21 inhibits N2 neutrophils polarization and promotes N1 neutrophils polarization, which transforms immunosuppressive TME into an anti-tumor context." (PMID 38367070, 2024). "CCR7 is expressed in both tumour and lymphoid tissues and activates B and T lymphocyte migration towards CCR7 ligands (CCL19 and CCL21)." (PMID 38762550, 2024). "TEV-derived miR-5110 promotes CCL21 secretion by downregulating pMC CD93, whereas C1q, increasing in tumor individuals, suppresses CD93-mediated CCL21 secretion." (PMID 38250037, 2024). "Elevated promoter methylation events involved 168 genes with reduced tumor expression, and it was notable that promoter hypermethylation of AMT, CCL21 and SPARCL1 were detected in the vast majority of tumors." (PMID 39104720, 2024). "Among these 23 TLSRGs, CCL19, CCL21 and IL1R2 were highly expressed in normal tissues, while the rest genes were highly expressed in tumor tissues." (PMID 39493749, 2024). "The levels of cytokines CCL21, eotaxin, CXCL1, CXCL2, CCL7, CCL19, and CCL25, which are capable of supporting tumor invasion, were reduced in CM from MSCs-TRAIL by 1.2, 1.3, 4-8, 3.4-1.3, 1.5, and 1.3 times, respectively (n = 3, ** p < 0.01)." (PMID 36661524, 2023). "Through interactions with CC chemokine ligand 21 (CCL21), which is generated by lymphatic endothelial cells, CCR7 promotes the mregDCs to migrate from primary tumours to lymph nodes." (PMID 36808888, 2023). "High plasma levels of CCL21 and presence of TLS-like regions in the tumor correlated with longer survival." (PMID 37377898, 2023). "A pervious paper has demonstrated that M1 macrophages, well-characterized activated macrophages with antitumorigenic properties, inhibit MC38 tumor growth and they express CCR7 and migrate toward a CCL21 gradient." (PMID 37664721, 2023). "Zhou and Ma later showed that VEGF-C/VEGFR3-mediated CCL21 expression promotes dendritic cell trafficking and subsequent CD8+ T cell activation, leading to attenuated tumor growth in mouse glioma models." (PMID 38201272, 2023). "In preclinical breast cancer studies, IL-7 is often combined with chemokines such as CCL19 and CCL21 to improve the chemotaxis of CAR T cells and other immune cells to the tumor site." (PMID 38201551, 2023). "Recent studies have shown that overexpression of IL-7 and CCL19 or C-C motif chemokine 21 (CCL21) within CAR-T cells can facilitate immune cell infiltration into tumors and support the persistence of CAR-T cells in the tumor microenvironment." (PMID 38516299, 2023). "In PAAD, sensory-neuron-derived mediators CXCL10 and CCL21 pass through complementary receptors CXCR3 and CCR7 on tumor cells, activating AKT, MEK, and RAC signaling pathways in tumor cells to mediate migration." (PMID 36900158, 2023). "CCR7 with its ligands CCL21 and CCL19 regulates the apoptosis of CD8 + T cells and participates in the process of tumor microenvironment remodeling." (PMID 37864213, 2023).